CXCR2 (C-X-C motif chemokine receptor 2)
Diseases named in the same sentence as CXCR2 in open-access papers (continued):
Sharing a sentence is not in itself a finding about the gene and the disease.
non-small cell lung carcinoma (16 papers, 2004 to 2025). A group of at least three distinct histological types of lung cancer, including non-small cell squamous cell carcinoma, adenocarcinoma, and large cell carcinoma. "Increased CXCR2 expression is also associated with poor prognosis, as shown by studies on acute myeloid leukemia, invasive ductal breast cancer, and non-small cell lung cancer." (PMID 38972952, 2024). "CXCL1 (Groα) gene encodes a secreted interleukine-like molecule binding specifically to G-protein-coupled receptor CXCR2 and potentially plays role in tumor-associated angiogenesis in non-small cell lung cancer." (PMID 26208990, 2015). "CXCR2 has significant protumour functions in a variety of tumours, including non-small cell lung cancer and PC." (PMID 40615400, 2025). "Similar encouraging outcomes of chemokine-modified CAR-T cells have been demonstrated in glioblastoma (CXCR1/CXCR2) and non-small-cell lung cancer (NSCLC) (CCR2B) xenograft models." (PMID 36853475, 2023). "We examined mRNA levels of CXCR1 and CXCR2 in a panel of non-small cell lung cancer cell lines including A549, H460, H358, H1299, and H322." (PMID 26087179, 2015). "The expressions of IL-8 and its receptors, CXCR1 and CXCR2, were examined in a panel of non-small cell lung cancer (NSCLC) and small cell lung cancer (SCLC) cell lines." (PMID 15545974, 2004). "It has been reported that CXCR2+ neutrophils are recruited by CXCL5 in tumor tissues to promote tumor progression in liver and non-small cell lung cancers." (PMID 34659209, 2021). "In addition, combined inhibition of CXCR2 and SHP2 in non-small cell lung cancer (NSCLC) models, selectively targeted a population of TANs with an immunosuppressive phenotype." (PMID 35158948, 2022).
rhabdomyosarcoma (16 papers, 2014 to 2025). A rare aggressive malignant mesenchymal neoplasm arising from skeletal muscle. "In agreement with this notion, the previous study has reported that inhibition of the PD-1/PD-L1 axis increases CD8(+) CTLs and inhibits rhabdomyosarcoma in CXCR2-deficient mice." (PMID 38505617, 2024). "Tumor trafficking of myeloid-derived suppressor cells is inhibited by CXCR2 deficiency in a mouse model of rhabdomyosarcoma and data from a mouse model of colitis-associated cancer suggests that CXCR2 is required for recruitment of myeloid-derived suppressor cells." (PMID 25372289, 2014). "For example, in rhabdomyosarcoma, CXCR2 inhibition reduces MDSC recruitment, a key barrier to the PD-1 response." (PMID 41163221, 2025). "In preclinical models of childhood cancers such as rhabdomyosarcoma, CXCR2+Ly6G+ cells mediate local immunosuppression, while CXCR2 inhibition improves immune checkpoint blockade efficacy." (PMID 35522219, 2022). "Accordingly, disrupting CXCR2-mediated MDSC trafficking to the TME was shown to enhance anti-PD-1 therapy response in a murine model of rhabdomyosarcoma." (PMID 33922556, 2021). "Consistently, CXCR2 is essential for Ly6GhiCD11b+ MDSCs trafficking into tumor tissues, but isn't required for these subsets to egress from the bone marrow in rhabdomyosarcoma." (PMID 29383101, 2017). "Therefore, we evaluated the activity of a dual CAR construct, expressing both B7-H3 CAR and human CXCR2, that had previously demonstrated superior activity in a rhabdomyosarcoma model." (PMID 38554158, 2024). "Evidence shows that CXCR2 mediates G‐MDSC tumor trafficking in murine rhabdomyosarcoma models." (PMID 34646521, 2021). "Additionally, disruption of CXCR2-mediated MDSC tumor trafficking enhances anti-PD1 efficacy in rhabdomyosarcoma, the most common childhood soft tissue sarcoma." (PMID 31390756, 2019). "Additionally, in rhabdomyosarcoma, CXCR2 inhibitor can inhibit CD11b+Ly6G+CXCR2+ MDSCs recruiting to tumor tissues and significantly enforce the anti-programmed cell death protein 1 (anti-PD1) immunotherapy efficacy in vivo." (PMID 29383101, 2017). "Notably, prevention of CXCR2-mediated MDSC trafficking by anti-CXCR2 mAb therapy enhances anti-PD-1 efficacy in a mouse model of rhabdomyosarcoma, suggesting a translatable strategy to improve the efficacy of immune checkpoint blockade therapy by preventing trafficking of MDSC to the tumor site." (PMID 27136535, 2016). "Disrupting MDSC and Treg trafficking, using inhibitors to CXCR2 and CXCR4, has been shown to enhance anti-PD-1 tumor response in rhabdomyosarcoma and hepatocellular carcinoma murine models, respectively." (PMID 33922556, 2021). "Similarly, in a murine model of rhabdomyosarcoma (RMS), treatment with an anti-CXCR2 antibody sensitized tumors to anti-PD1 treatment." (PMID 34944914, 2021). "In addition, we demonstrated that co-expressing a chemokine receptor (CXCR2) with the CAR construct significantly improved overall canine CAR T cell anti-tumor activity, consistent with our previous work demonstrating enhanced human CAR T cell activity against rhabdomyosarcoma." (PMID 38554158, 2024).
Arthritis (15 papers, 2010 to 2026). Inflammation of a joint. "In addition, CXCR1 haplotypes differed between patients with arthritis and erythema nodosum compared to controls, while CXCR2 haplotypes were significantly associated with genital and ocular involvement." (PMID 41596568, 2026). "CXCR2 expressed on neutrophils has been reported to play a critical role in the recruitment of neutrophils in preclinical models of arthritis, allergy, respiratory disease, and ulcerative colitis." (PMID 39062109, 2024). "In conditions such as arthritis, CXCR2 mediates the recruitment of neutrophils to inflamed joints, contributing to synovial inflammation and joint destruction." (PMID 39062109, 2024). "Our findings demonstrate that CXCL5 activates CXCR2 in nociceptor neurons to drive acute gout arthritis pain and joint inflammation." (PMID 38627393, 2024). "CXCL8-based decoy proteins prevented CXCR1 and CXCR2 signaling in neutrophils and ameliorated arthritis in AIA mice." (PMID 36860872, 2023). "CXCL1 and CXCL8 induce neutrophil chemotaxis in vitro, which is also inhibited by the blockade of CXCR1/CXCR2 and DF 2162, the later inhibiting neutrophil recruitment in zymosan-induced arthritis in mice and AIA in rats." (PMID 36860872, 2023). "Therapeutic blockade of CXCR2 can rapidly clear inflammation in arthritis and atopic dermatitis models." (PMID 35707715, 2022). "The CXCL2 receptor CXCR2 is required for the development of full pathology in K/BxN arthritis, and in particular for neutrophil recruitment." (PMID 23071771, 2012). "In this regard, a sequential role for the leukotriene B4 receptor Blt1, Ccr1 and Cxcr2 has previously been reported for neutrophil recruitment in a mouse model of arthritis." (PMID 22916017, 2012). "Accordingly, although arthritis in Il17ra−/− mice was attenuated in all phases, the more pronounced clinical difference was found in the second phase of arthritis when the arthritis is amplified and maintained by CXCR2 chemokine ligands." (PMID 22028860, 2011). "Neutralizing CXCR2, a neutrophil chemokine receptor, reduced arthritis severity in Il1rn−/−Ccr2−/− mice." (PMID 21991368, 2011). "We have recently shown that CCR1 and CXCR2 are needed for the development of full-blown serum-induced arthritis." (PMID 22028860, 2011). "CXCR2 was found to be critical for the development of autoantibody-mediated arthritis, and neutrophil recruitment to the joints." (PMID 20738854, 2010). "Double-knockout mice for CCR1 and CXCR2 have been studied for research on arthritis." (PMID 38750114, 2024). "Furthermore, the blockade of CXCR1 and CXCR2 (DF 2162) ameliorated arthritis by inhibiting neutrophil migration in AIA rats." (PMID 36860872, 2023). "Since our collagen-induced arthritis model is different from the Il1rn-dependent model in which polyarthritis develops spontaneously, it is difficult to compare directly which therapeutic method, anti-IL-17A or anti-CXCR2 is more effective." (PMID 21991368, 2011). "In a mouse model of arthritis, CCR1 increased neutrophil crawling on the endothelium, while CXCR2 increased neutrophil retention and survival within the joints." (PMID 38750114, 2024). "Nevertheless, these data suggest that the local induction of CXCR2 and CCR1 chemokines in the synovium is likely the major mechanism of the amplification of serum-induced arthritis by IL-17RA signaling." (PMID 22028860, 2011). "We have recently shown that CCR1 and CXCR2 play crucial non-redundant roles in serum-induced arthritis and together account for all of the neutrophil chemokine activity in the model." (PMID 22028860, 2011). "Utilizing several strains of chemokine receptor-knockout mice, these authors found that CXCR2, not CCR1, was important in their pre-clinical arthritis mouse model." (PMID 25170619, 2014).
lung diseases (14 papers, 2011 to 2025). "Activation of the Il-1 family of cytokines is downstream of Cxcr2 activation and aberrant expression of the Il-1 family has been implicated in pulmonary diseases such as new BPD." (PMID 36976210, 2023). "In both pulmonary diseases, a functional role for CXCR2 has been implicated." (PMID 22936934, 2012). "Furthermore, acute exacerbations of these pulmonary diseases are associated with increased neutrophilic inflammation in the airways so CXCR2 antagonists may be effective in preventing and treating exacerbations." (PMID 24341382, 2013). "Although F2TCDD and F2TCDD/Form pups frequently exhibited new BPD, paternal fish oil supplementation attenuated the expression of pulmonary inflammation (Cxcr2, Il-1 alpha, and Tlr4) and significantly reduced the incidence of lung disease in offspring." (PMID 36976210, 2023). "Because of the promising results in animal models, these CXCR2 antagonists are now being tested in clinical trials for lung diseases." (PMID 35682923, 2022). "Several clinical trials targeting CXCR2 or ELR+ chemokines in pulmonary disorders are currently underway." (PMID 33123138, 2020). "As further clinical trial data with CXCR2 antagonists emerge in NET-rich lung diseases, it will be important to dissect how well the steroid-resistant phenotypes respond to these neutrophil-trafficking CXCR2 inhibitors." (PMID 30804927, 2019). "A similar effect on lung disease is seen in mice with antagonism of a chemokine receptor, C–X–C chemokine receptor 2 (CXCR2), expressed predominantly on circulating granulocytes and endothelial progenitor cells." (PMID 30081463, 2018). "Our observations support the development of AZD8309 and other CXCR2 antagonists for the treatment of inflammatory pulmonary and non-pulmonary diseases characterized by neutrophilia." (PMID 24341382, 2013). "Thus, our findings indicate that targeted inhibition of CXCR1/CXCR2 attenuates pulmonary phenotypes caused by ATM-deficiency and suggest that this treatment approach represents a viable therapeutic strategy for A-T lung disease." (PMID 33608602, 2021). "Due to its expression on lung endothelial and epithelial cells, it is not surprising that CXCR2 has been implicated in different lung diseases." (PMID 22936934, 2012). "CXCR2 antagonists have been explored in non-cancer lung diseases (e.g., NCT01255592, NCT01006616) and in certain cancers such as castration-resistant prostate cancer (NCT03177187) and squamous cell carcinoma of the head and neck (NCT02499328)." (PMID 36986488, 2023). "In the current study, we find that reparixin attenuates key inflammatory phenotypes in our preclinical mouse model of A-T lung disease, thereby indicating that antagonism of CXCR1/CXCR2 may represent an effective therapeutic strategy for this frequent cause of death in A-T patients." (PMID 33608602, 2021).
Obesity (14 papers, 2009 to 2025). Accumulation of substantial excess body fat. "Taken together, the adipocyte-specific CXCR2 cKO was associated with obesity-induced ascites despite a reduced tumor burden, likely altering the peritoneal tumor microenvironment of OC." (PMID 34638514, 2021). "Together, these results indicate that CXCL1 signalling via CXCR1 and CXCR2 mediates the obesity-associated stimulation of tumour growth." (PMID 27241286, 2016). "Furthermore, bone marrow chimera mice deficient in the KC receptor CXCR2 showed a decrease in obesity-induced inflammation and insulin resistance compared to controls." (PMID 34571976, 2021). "As a future research direction, the quantitative analysis of physiological aspects, such as the food intake pattern, fat distribution, and lipid metabolism, may give an important insight to clarify the underlying mechanisms affecting the roles of CXCR2 in obesity." (PMID 34638514, 2021). "Atherosclerosis isanother obesity-related risk factor in which CXCR2 could play an importantrole." (PMID 20157549, 2009). "Preventing the aging of neutrophils via selective ablation of CXCR2, reduces the development of obesity and improves the sensitivity to insulin." (PMID 38327649, 2023). "Our main finding from the present study is that adipocyte-specific CXCR2 cKO resulted in a lower tumor burden but increased the OC-induced ascites under obesity-inducing diet conditions." (PMID 34638514, 2021). "Recent data have shown that, along with CXCL5, circulating levels of CXCL1, with high affinity to CXCR2, are markedly increased in the db/db mice and correlate with obesity development." (PMID 34571976, 2021). "The adipose tissues in HFD-fed WT mice showed a larger increase in CXCR2 protein levels compared to ND-fed mice, indicating an obesity-induced CXCR2 expression." (PMID 34638514, 2021). "This indicated that adipocyte-specific CXCR2 cKO was related to the obesity-induced accumulation of ascites in OC." (PMID 34638514, 2021). "Adipocytes and OC cells highly express CXCR2, and its ligands CXCL1/8, respectively, indicating that the CXCL1/8-CXCR2 axis is a molecular link between obesity and OC." (PMID 34638514, 2021). "Despite the ascites accumulation, adipocyte-specific CXCR2 cKO reduced the obesity-induced tumor burden, likely altering the peritoneal tumor microenvironment of OC." (PMID 34638514, 2021). "Another possibility being the dependence of neutrophil chemotaxis on CXCL5 (LIX), binding both CXCR1 and CXCR2, which levels are also increased in obesity." (PMID 33673387, 2021). "In conclusion, high fat diet-induced obesity suppressed the protein expression of IL-7, IL-8, IL-6, CXCR2, and VEGF in skeletal muscle." (PMID 32295130, 2020). "Accordingly, targeting CXCR2 may be critical in blocking the obesity-induced progression of OC." (PMID 34638514, 2021). "Interestingly, mouse adipocytes expressed higher levels of CXCR2 mRNA compared to preadipocytes and OC progression could be accelerated by an obesity-induced inflammatory burden." (PMID 34638514, 2021). "Indeed, the role of the CXCR2 pathway in obesity-induced inflammatory response was confirmed by the observation that a CXCR1/2 inhibitor was effective in the db/db mouse model in reducing neutrophil and macrophage infiltration in the liver and in the adipose tissue." (PMID 34571976, 2021). "Previous studies have reported CXCR2 and CCR2 as molecular players involved in the development of obesity-induced inflammation and insulin resistance." (PMID 38989000, 2024). "Based on the high expression levels of CXCL1–3 and CXCL8 in OC cells and the high levels of CXCR2 in adipocytes, the CXCL1/8-CXCR2 axis is proposed as a molecular link between obesity and OC." (PMID 34638514, 2021). "CXCR2 transfected OC cells expressed higher levels of CXCL1/2 compared to CXCR2 null OC cells and obesity-induced, higher circulating CXCL1 levels, indicating a positive feedback loop." (PMID 34638514, 2021).
Obesity (continued). "In this study, while the expression patterns of IL-8, CXCR2, and VEGF decreased in obesity, it was found to be markedly activated after exercise training." (PMID 32295130, 2020). "Concurrently, obesity increases intratumoral CXCL1 concentrations, promoting CXCR2-mediated accumulation of FasL+ G-MDSCs, resulting in heightened Fas/FasL-mediated CD8 TIL apoptosis and immunotherapy resistance." (PMID 33123173, 2020). "Primary examples include chemokine receptors (CXCR1, CXCR2, CXCR4, CCR5, CCR7) that drive chronic inflammatory responses common to both obesity and cancer." (PMID 33329395, 2020). "Combined, our results suggest that in patients, CXCR1 expressed in ASCs in vivo, and possibly CXCR2, direct ASC trafficking towards CXCL8 gradient activated in cancer and CXCL1 gradient in addition activated in obesity." (PMID 27241286, 2016). "CXCR2 KO mice (C129S2(B6)-Cxcr2tm1Mwm/J mice, Jackson Laboratory) were not susceptible to diet-induced obesity, showing a lower weight gain." (PMID 34638514, 2021). "Although our results supported a shorter survival in OC patients with obesity, adipocyte-specific CXCR2 cKO was not likely to critically affect the survival of OC." (PMID 34638514, 2021). "As obesity increases the risk of OC progression and leads to enhanced tumor burden, HFD-induced obesity resulted in a shorter survival regardless of the CXCR2 in adipose tissues." (PMID 34638514, 2021). "Thus, we have identified a pathway wherein obesity leads to increased intratumoral CXCL1 concentrations, which promotes CXCR2-mediated accumulation of FasL+ G-MDSCs, resulting in heightened CD8 TIL apoptosis and immunotherapy resistance." (PMID 33123173, 2020). "To assess whether ASCs could be recruited in response to CXCL1 secreted by tumours in obesity, we performed immunofluorescence analysis of CXCR1 and CXCR2, the receptors of CXCL1 and CXCL8." (PMID 27241286, 2016). "However, the global deletion of CXCR2 using KO mice is not suitable for a diet-induced obesity model due to fewer and smaller adipocytes in this KO mouse model." (PMID 34638514, 2021). "In this study, the skeletal muscle expression of IL-8, CXCR2, and VEGF was lower in obese rats compared to non-obese rats, consistent with the notion that obesity negatively impacts angiogenesis." (PMID 32295130, 2020). "Crown-like structures in the adipose tissues were not different between CXCR2 WT and cKO mice but there was an approximate 2-fold increase in both HFD-fed mice, indicating the stimulation of the proinflammatory processes in the adipose tissue due to obesity in HFD-fed mice." (PMID 34638514, 2021). "Additionally, mice lacking CXCR2 show resistance to the onset of obesity-induced disorders of glucose metabolism, and a recent study found that SDF-1/CXCL12, which is secreted from hypertrophic adipocytes, recruits macrophages via CXCR4, which is the receptor of SDF-1/CXCL12, during obesity." (PMID 26197341, 2015).